HP (haptoglobin)
Diseases named in the same sentence as HP in open-access papers (continued):
Sharing a sentence is not in itself a finding about the gene and the disease.
Cachexia (2 papers, 2020 to 2023). Severe weight loss, wasting of muscle, loss of appetite, and general debility related to a chronic disease. "Haptoglobin is synthesized by the lung during inflammation, skeletal muscle during cachexia, and tumor microenvironment where it causes cellular changes, which promote metastasis." (PMID 38022578, 2023). "Haptoglobin protein levels are increased in a ciliary neurotrophic factor induced cachexia rat model and cachexia associated with congestive heart failure in human patients." (PMID 38022578, 2023). "Bonetto and colleagues have also shown an increased serum haptoglobin in the C26 cancer cachexia mouse model, in addition to several other acute phase proteins." (PMID 38022578, 2023). "Our results revealed a marked increased muscular production of several acute phase reactants (APR: Haptoglobin, Serine protease inhibitor A3N, Complement C3, Serum amyloid A-1 protein) which are released in the circulation during C26 cancer cachexia." (PMID 33142864, 2020).
cardiac arrest (2 papers, 2011 to 2016). Cessation of breathing and/or cardiac function. "Haptoglobin is also considered an acute phase reactant and is increased in patients after cardiac arrest." (PMID 27165192, 2016). "Haptoglobin and fibrinogen levels were high due to cardiac arrest as they are acute phase reactants." (PMID 21712882, 2011).
cerebral palsy (2 papers, 2023 to 2025). A group of disorders affecting the development of movement and posture, often accompanied by disturbances of sensation, perception, cognition, and behavior. "Cord blood haptoglobin, cerebral palsy and death in infants of women at risk for preterm birth: a secondary analysis of a randomised controlled trial." (PMID 40964021, 2025).
Chagas disease (2 papers, 2014 to 2023). A parasitic infection caused by Trypanosoma cruzi. "Only two studies have so far addressed the possible association between HP polymorphism and the pathogenesis of Chagas disease." (PMID 25147423, 2014). "The second study investigated the possible association between haptoglobin genotypes and the severity of the Chagas disease." (PMID 25147423, 2014). "Their study found that while the HP2 allele appears to confer increased risk for developing serious complications of heart disease, those patients with genotype HP1-1 were less likely to develop the heart disease, implying that HP polymorphism may influence the clinical course of Chagas disease." (PMID 25147423, 2014). "Therefore, because of the role of haptoglobin in the immune response and previous studies pointing to an association of HP genotypes with Chagas disease progression, we investigated the association of haptoglobin gene polymorphisms in Venezuelan patients with chronic Chagas disease." (PMID 25147423, 2014).
cholestasis (2 papers, 2008 to 2017). Impairment of the bile flow caused by obstruction within the liver, or outside the liver in the bile duct system. "The most frequently identified cause of FibroTest failure was false negatives attributable to inflammation, with an isolated increase in haptoglobin (four cases); one false-positive FibroTest result was attributable to hemolysis, and one to posttransplantation fibrosing cholestasis." (PMID 19568532, 2008).
chorioamnionitis (2 papers, 2021 to 2025). A morphologic finding indicating inflammation of the fetal sac membranes. "Maternal cytokines were quantified by multiplex immunoassay, and fetal inflammatory exposure (Triple I) assessed using histological chorioamnionitis (HCA), cord blood haptoglobin, and IL-6." (PMID 40964021, 2025). "Of the variables supporting the presence of intrauterine inflammation and a foetal biochemical response, funisitis and serum α1-AG levels, but not chorioamnionitis or serum CRP and haptoglobin levels, showed robust associations with the development of MAS." (PMID 34408219, 2021).
coagulopathy (2 papers, 2022 to 2025). "Low levels of haptoglobin have previously been used as a marker of coagulopathy in snakebite victims, a pathology not often associated with B. gabonica and B. arietans envenoming." (PMID 35448838, 2022).
dementia (2 papers, 2015 to 2018). Loss of intellectual abilities interfering with an individual's social and occupational functions. "Reports also show that dementia is related to peripheral pro-inflammatory factors released by periodontal inflammatory mediators such as C-reactive protein, IL-6, haptoglobin, TNF-α, and fibrinogen." (PMID 29740354, 2018).
E. coli infection (2 papers, 2016 to 2022). "In the present study, E. coli infection induced the significant up-regulation of many AMPs including cathelicidins, beta defensins, S100A calcium binding proteins, lactoferrin and haptoglobin." (PMID 36009735, 2022).
Evans syndrome (2 papers, 2021 to 2024). "Although hemolytic anemia was suspected, it was unlikely as there were no changes in haptoglobin or LDH, reducing the possibility of Evans syndrome, a complication of AITL." (PMID 39364516, 2024).
falciparum malaria (2 papers, 2012 to 2015). "Plasma levels of haemin (oxidized haem), haemopexin, haptoglobin, and haemoglobin were quantified in a case–control study of Ugandan children with Plasmodium falciparum malaria." (PMID 26691827, 2015). "ROC curves demonstrate apolipoprotein A-I (AUC = 0.957) and haptoglobin (AUC = 0.936) as efficient predictor proteins for falciparum malaria detection." (PMID 22912677, 2012).
Fungal infection (2 papers, 2013 to 2022). "Fungal infection of cornea clearly induce increased expression of alpha 1 antitrypsin, apolipoprotein, haptoglobin, albumin, zinc α 2 glycoprotein (ZAG), lactoferrin, haptoglobin precursor, proteins related to inflammatory events." (PMID 23308132, 2013). "Although the direction of haptoglobin changed in this study is consistent with that of a study of fungal infections in quail, we did not detect high mortality or other signs indicating a negative impact on the health or productive performance of laying hens in our study." (PMID 35477136, 2022).
gestational diabetes (2 papers, 2021 to 2024). Carbohydrate intolerance first diagnosed during pregnancy. "This study aimed to assess whether the Haptoglobin (Hp) genotype influences the relationship between hemoglobin (Hb) levels and the development of gestational diabetes mellitus (GDM)." (PMID 38951151, 2024).
glaucoma (2 papers, 2024). Increased pressure in the eyeball due to obstruction of the outflow of aqueous humor. "Our study identified and validated six neuroinflammation-related hub genes in glaucoma (SERPINA3, LCN2, MMP3, S100A9, IL1RN, and HP)." (PMID 39125762, 2024).
Guillain-Barre syndrome (2 papers, 2011 to 2023). A spectrum of rare post-infectious neuropathies that usually occur in otherwise healthy patients. "Increased CSF haptoglobin levels have also been observed in traumatic brain injury, AD, and Guillain-Barre syndrome, suggesting that increased CSF haptoglobin is not specific to MS pathophysiology but may have long-term prognostic value for MS." (PMID 37339131, 2023).
haemorrhagic septicemia (2 papers, 2016 to 2019). "They observed increasing concentration of serum haptoglobin up to 7 folds in induced cases of haemorrhagic septicemia in Brangus heifers." (PMID 26961495, 2016).
hemolytic-uremic syndrome (2 papers, 2011 to 2018). Acute kidney injury associated with microangiopathic hemolytic anemia and thrombocytopenia. "The hemolytic-uremic syndrome (HUS) is defined by the association of hemolytic anemia (low haptoglobin levels, high lactate deshydrogenase levels, and schistocytes), thrombocytopenia, and acute renal failure." (PMID 21876803, 2011).
hemorrhagic stroke (2 papers, 2020 to 2024). A stroke caused by a bleed on the brain. "Research has shown that, in models of traumatic brain injury (TBI) and hemorrhagic stroke, haptoglobin expression is upregulated as a compensatory mechanism to mitigate hemoglobin toxicity." (PMID 39765770, 2024).
herpesvirus infection (2 papers, 2017 to 2024). "Plasma HP concentration has been previously associated with herpesvirus infection in frigatebird nestlings and was predictive of short-term survival." (PMID 38983768, 2024). "Our results showed that the plasma concentration of haptoglobin was greatly increased during a disease probably caused by herpesvirus infection and might predict the short-term probability of survival of frigatebird nestlings." (PMID 28070333, 2017). "The haptoglobin test had higher sensitivity and specificity than nitric oxide for herpesvirus infection." (PMID 28070333, 2017).
hidradenitis suppurativa (2 papers, 2025). A chronic suppurative and cicatricial disease of the apocrine glands occurring chiefly in the axillae in women and in the groin and anal regions in men. "Haptoglobin expression was analysed and compared between skin lesions of patients with hidradenitis suppurativa (HS) and healthy controls, as well as between different anatomical regions affected by HS." (PMID 40430166, 2025).
Hyperinsulinemia (2 papers, 2020 to 2024). An increased concentration of insulin in the blood. "Haptoglobin is a glycoprotein involved in the acute-phase response to inflammation and its increase in obese subjects seems to be a strong marker of hyperinsulinemia and inflammation." (PMID 32932852, 2020).
hypopituitarism (2 papers, 2021 to 2025). A condition of diminution or cessation of secretion of one or more hormones from the anterior pituitary gland. "However, while our study implicates isoflurane in the induction of hypogonadism and hypopituitarism via suppression of HP function, human studies suggest that TBI‐induced hypogonadism and hypopituitarism is mediated via suppression of HP function by elevated circulating cortisol." (PMID 34277964, 2021).
inflammatory bowel disease (2 papers, 2012 to 2022). A spectrum of small and large bowel inflammatory diseases of unknown etiology. "In the plasma of the AB pigs, we found a significantly lower abundance of haptoglobin (spot 1207, 1209 1217, 2011, 2212, 3012), which has been linked to inflammatory bowel disease." (PMID 23028687, 2012).
influenza (2 papers, 2023 to 2024). An acute viral infection of the respiratory tract, occurring in isolated cases, in epidemics, or in pandemics; it is caused by serologically different strains of viruses (influenzaviruses) designated A, B, and C, has a 3-day incubation period, and usually lasts for 3 to 10 days. "The nomogram model, based on the expression levels of MPO and HP and the duration of illness, was verified as a reliable prediction model for severe influenza." (PMID 39340342, 2024). "A nomogram based on the expression levels of MPO, HP, and duration of illness is an efficient model for the early identification of patients with severe influenza." (PMID 39340342, 2024). "Multivariate logistic regression demonstrated significant correlations between severe influenza and myloperoxidase (MPO) level, haptoglobin (HP) level, and duration of illness." (PMID 39340342, 2024). "The nomogram for severe influenza, based on the expression levels of MPO and HP and duration of illness, was demonstrated to have good discrimination, calibration, and clinical value." (PMID 39340342, 2024). "LASSO analysis showed that severe influenza was significantly correlated with duration of illness, age, bacterial status, DEFA3, HP, and MPO." (PMID 39340342, 2024).
Jaundice (2 papers, 2021 to 2023). Yellow pigmentation of the skin due to bilirubin, which in turn is the result of increased bilirubin concentration in the bloodstream. "The results presented here indicate that the levels of XO in plasma are associated with SMA, but also with hemolysis-related parameters (haptoglobin, LDH, HO-1 and bilirubin), as well as with related complications such as jaundice." (PMID 37679382, 2023).
joint disease (2 papers, 2017 to 2019). "Fibrinogen is involved in hemokinesis and Kong have identified three proteins (apolipoprotein, haptoglobin precursor, and fibrinogen D fragment) that are related to joint diseases in OA SF samples by one and two dimension electrophoresis." (PMID 30795769, 2019). "There are no studies reporting the use of haptoglobin for diagnostic purposes in joint disease yet." (PMID 28629364, 2017).
kidney (2 papers, 2016 to 2018). "Data from mouse models subjected to acute kidney injury with multiple agents revealed relatively greater and sustained increase in renal (proximal tubules) expression of HP as compared to hepatic HP expression." (PMID 29572449, 2018).
leptospirosis (2 papers, 2012 to 2024). A contagious bacterial infection caused by spirochetes of the genus Leptospira. "The mean haptoglobin concentration was found to be 0.208±0.048 and 0.333±0.06 g/L in FM and VM patients respectively, while the healthy and leptospirosis (FC) populations exhibited a mean values of 0.918±0.1 g/L and 0.888±0.056 g/L (mean ± SE)." (PMID 22912677, 2012).
lymph node metastasis (2 papers, 2016 to 2024). "Further analysis using univariate and multivariate Cox regression showed that TNM stage, lymph node metastasis status, pathological distant metastasis status, and serum haptoglobin levels were independent risk factors of prognosis of NSCLC patients." (PMID 27248178, 2016). "Unfavorable clinicopathological variables, TNM stage, lymph node metastasis, and distant metastasis, were associated with high serum haptoglobin levels." (PMID 27248178, 2016). "Higher serum haptoglobin levels were associated with advanced TNM stage, lymph node metastasis, and distant metastasis." (PMID 27248178, 2016). "The area under the ROCs for the detection of NSCLC lymph node metastasis by serum haptoglobin was 0.609 (sensitivity of 0.672, specificity of 0.554), suggested that haptoglobin might be associated with the progression and poor prognosis of NSCLC." (PMID 27248178, 2016). "In summary, our results showed that serum haptoglobin levels significantly elevated in NSCLC patients compared with normal healthy controls, and there was a strong association between high serum haptoglobin levels and TNM stages, lymph node metastasis, and distant metastasis." (PMID 27248178, 2016). "We verified whether serum haptoglobin levels associated with NSCLC lymph node metastasis or not." (PMID 27248178, 2016). "In NSCLC, several studies have found significantly elevated levels of haptoglobin in tumor tissues as well as in patient serum compared to normal controls, and suggested that high levels of haptoglobin correlate with TNM staging, lymph node metastasis, and distant metastasis." (PMID 39872525, 2024). "Furthermore, the serum haptoglobin levels were obviously higher in patients with lymph node metastases than those without (2.136 ± 1.077 mg/mL, 1.719±0.917 mg/mL, respectively, P = 0.0356)." (PMID 27248178, 2016).
malignant hypertension (2 papers, 2017 to 2022). Severe hypertension that is characterized by rapid onset of extremely high blood pressure and hypertension-mediated organ damage. "Interestingly, in a recent study in 20 patients with malignant hypertension, half of patients had low haptoglobin, and 12 patients had reversible encephalopathy syndrome." (PMID 35057750, 2022).
meningitis (2 papers, 2021 to 2023). A disorder characterized by acute inflammation of the meninges of the brain and/or spinal cord. "The biomarkers of inflammation haptoglobin and ITIH4 showed higher levels in pigs with meningitis than controls (1.5 and 1.6-fold, respectively)." (PMID 37525237, 2023).
metastatic cancer (2 papers, 2015 to 2021). A carcinoma which has spread from the original site of growth to another anatomic site. "Additionally, our haptoglobin scaffolds provide a synthetic pre-metastatic niche for capturing circulating tumor cells, which has implications in metastatic cancer detection, diagnosis, and therapy." (PMID 26634905, 2015). "Therefore, in the observed tissues, SPARCL1 was most highly expressed in normal colorectal tissues, and CDH2 had the highest expression in normal liver tissues and liver metastatic cancer tissues, while CP, HP, TF, and SERPINA5 with the most highly expressed in normal liver tissues." (PMID 34422629, 2021). "We also observed CDH2, CP, HP, TF, and SERPINA5 were upregulated in liver metastatic cancer tissues and downregulated in primary cancer tissues; whereas SPARCL1 exhibited the opposite expression pattern." (PMID 34422629, 2021).
metastatic disease (2 papers, 2015 to 2024). "This in vivo result, coupled with our in vitro validation studies, is the first demonstration of haptoglobin mediating tumor cell homing to a defined niche, and implicates haptoglobin as a factor contributing to the spread of metastatic disease." (PMID 26634905, 2015).
methemoglobinemia (2 papers, 2014 to 2020). An inherited or acquired condition characterized by abnormally increased levels of methemoglobin in the blood. "While we cannot exclude low level hemolysis lowering haptoglobin concentrations, this was insufficient to produce methemoglobinemia, lower hemoglobin levels, hematocrit and reticulocyte percentage, or increase indirect bilirubin and AST." (PMID 33007039, 2020). "During the hemolytic crisis there may be methemoglobinemia and hemoglobinuria, the concentration of haptoglobin is reduced, and the LDH levels are greatly increased." (PMID 25371680, 2014).
Mitral regurgitation (2 papers, 2015 to 2020). An abnormality of the mitral valve characterized by insufficiency or incompetence of the mitral valve resulting in retrograde leaking of blood through the mitral valve upon ventricular contraction. "High-density lipoprotein, apolipoprotein-A1, haptoglobin and haptoglobin-α2 chain levels significantly decreased proportionally to the degree of mitral regurgitation when compared to controls." (PMID 26405438, 2015).
Myeloid Leukaemia (2 papers, 2022 to 2025). "A function of HP and HPR in myeloid leukemia is yet to be determined." (PMID 36230605, 2022).
nephrotic syndrome (2 papers, 2022). A collection of symptoms that include severe edema, proteinuria, and hypoalbuminemia; it is indicative of renal dysfunction. "The increase in α2 macroglobulin in the nephrotic syndrome, as well as the increase in haptoglobin in the inflammation of the liver, occurred as a result of arsenic poisoning." (PMID 35035501, 2022). "In addition, as a biomarker of diabetic cardiovascular disease and steroid-resistant nephrotic syndrome, haptoglobin can also be used to evaluate and diagnose diarrhea in calves due to its significantly increased expression in calves with DHD." (PMID 36204290, 2022).
nosocomial infection (2 papers, 2015 to 2025). An infection acquired in a hospital or other healthcare setting. "The remaining transcriptomic candidates of the heme degradation pathway (HP, CD163, HMOX1; IL-10) and IL-8 clustered together, with moderate correlation to nosocomial infections (lower half of the heatmap)." (PMID 26607226, 2015).
oral cancer (2 papers, 2011 to 2021). "For instance, increased expression of alpha-2-macroglobulin, haptoglobin, and mucin-5B on oral cancer-derived sEVs could serve as biomarkers for oral cancer diagnosis." (PMID 33791224, 2021).
oral squamous cell carcinoma (2 papers, 2019 to 2023). "Four of these studies found a higher level of haptoglobin in patients with oral squamous cell carcinoma (OSCC) or laryngeal cancer, compared to controls, in agreement with our finding." (PMID 37876941, 2023). "On the contrary, RBP4 was recently reported as a potential biomarker of oral squamous cell carcinoma, in combination with clusterin, haptoglobin, complement C3c, and proapolipoprotein A1." (PMID 30813269, 2019).